FASN (fatty acid synthase)
Diseases named in the same sentence as FASN in open-access papers (continued):
Sharing a sentence is not in itself a finding about the gene and the disease.
tumor (continued). "To assess alterations in PITPNC1/FASN/CD155 within tumor cells and their direct modulation of CD8+ T cell functionality, we conducted the isolation of individual CD8+ T cells." (PMID 38291470, 2024). "Upregulation of FASN enhances CRC growth and spread through the AMPK/mTOR signaling pathway and is associated with secondary lymph node involvement, tumor stage (TNM), and poorer CRC outcomes." (PMID 39119332, 2024). "This study reveals the complex energy dynamics of BC, exploring the interplay between two crucial metabolic regulators, FASN and LDHA, and disease progression unveiling patterns linked to tumor aggressiveness and treatment response." (PMID 39044184, 2024). "FASN is emerging as a key driver of the activation, differentiation, and functionality of immune cells in the tumor microenvironment (TME)." (PMID 39349429, 2024). "Tumors generally stimulate the fatty acid synthase to promote lipid synthesis and meet the lipid requirement for tumor cell proliferation." (PMID 39170694, 2024). "Knockdown of POU6F2-AS1 markedly inhibited cell growth and decreased tumour volume and weight, but FASN overexpression reversed these effects induced by POU6F2-AS1 knockdown, as demonstrated by the increases in cell growth and tumour volume and weight." (PMID 38491348, 2024). "We then explored the potential role of MPC2 in supporting AR-driven tumour reprogramming towards a lipogenic phenotype, by measuring the expression of both AR and FASN in our samples." (PMID 39013948, 2024). "In various tumor types, such as colon, stomach, breast, lung, prostate, and ovarian carcinomas, elevated levels of FASN expression have been observed in comparison to normal tissues." (PMID 38731601, 2024). "Through such a multifaceted approach, we now provide evidence that FASN is a tumor cell-intrinsic metabolic determinant that disfavors immune-mediated cytolysis." (PMID 39349429, 2024). "Orlistat can act as an antitumor agent as it inhibits fatty acid synthase, decreases tumor cell proliferation, and stimulates tumor cell apoptosis." (PMID 38672673, 2024). "The fatty acid synthase inhibitor TVB-2640 has shown strong anti-tumor effects and has demonstrated good therapeutic efficacy and manageable safety in clinical trials." (PMID 39744129, 2024). "A study found that KDM5C, a histone H3K4-specific demethylase, can repress FASN-mediated lipid metabolism to exert tumor suppressor activity in ICC." (PMID 38648205, 2024). "There is also a positive loop between FASN and AKT, as FASN inhibition by TVB‐3166 has demonstrated to downregulate PI3K‐AKT–mTOR axis reducing tumor growth in Kras mutant NSCLC mice." (PMID 38425123, 2024). "The role of FASN as a novel tumor cell-intrinsic metabolic checkpoint that impairs T-cell immunity can be exploited to improve the clinical efficacy of immunotherapy." (PMID 39349429, 2024). "The results of the cell proliferation assays demonstrated that knockdown of FASN inhibited tumor cell proliferation and enhanced the anti-tumor effect of ADM." (PMID 39345091, 2024). "During tumorigenesis, there is increased expression of FASN, along with increased enzymatic activity; as much as 90% of fatty acids present in tumor cells are due to de novo endogenous fatty acid synthesis." (PMID 38112617, 2024). "Transcriptomic analysis was conducted on 725 BC samples, categorized by tumor grade, to explore the expression patterns of FASN and LDHA across the progression of the disease." (PMID 39044184, 2024). "An increase in fatty acid synthase (FASN), a key enzyme of de novo lipogenesis, has been reported to promote tumor growth and cell proliferation." (PMID 38791327, 2024). "FASN, also a central regulator of de novo lipogenesis, plays a pivotal role in tumor growth and serves as a fuel source for ATP generation." (PMID 39309439, 2024). "FASN inhibitors selectively induce programmed cell death in different tumor cells while sparing normal cells since only a small number of normal cells depend on FASN." (PMID 38540154, 2024).
tumor (continued). "Docosahexaenoic acid (DHA), an omega-3 polyunsaturated fatty acid, promotes the degradation of PD-L1 by inhibiting the expression of FASN, and then reverses the PD-L1-mediated immunosuppression, thus inhibiting tumor growth." (PMID 38272906, 2024). "In TNBC, the inhibition of FASN expression can overcome chemotherapy resistance in tumor cells, demonstrating a consistent indirect anti-tumor effect." (PMID 38481820, 2024). "Inhibition of fatty acid synthase (FASN) revealed a distinct tumor response, which were exacerbated by proliferative potential and mitochondrial respiration." (PMID 39484162, 2024). "The investigation revealed that downregulation of PITPNC1 led to apoptosis in radioresistant cells, whereas direct inhibition of FASN indirectly suppressed the expression of CD155 on tumor cell surfaces." (PMID 38291470, 2024). "The in vivo data indicate that SKP2 is a critical contributor to AKT-dependent hepatocarcinogenesis downstream of FASN via its ability to downregulate the p27KIP1 tumor suppressor." (PMID 39064589, 2024). "Studies have shown that the activation of the sterol regulatory element-binding protein 1/fatty acid synthase (SREBP1/FASN) signaling pathway can inhibit the apoptosis of tumor cells induced by radiotherapy." (PMID 38291470, 2024). "As a result, blocking fatty acid synthase has been proposed to be a promising and effective strategy to prevent tumor growth, as past studies have shown that FASN inhibitors are effective in this regard." (PMID 38339301, 2024). "During initial tumorigenesis, FASN is a key component of the immunoediting metabolic program that supports tumor immune evasion." (PMID 39349429, 2024). "Fatty acid synthase (FASN) meets the energy requirements of tumor cells during growth and proliferation by de novo synthesizing of FAs, and promotes various malignant phenotypes in tumors." (PMID 38581001, 2024). "Consistently, we demonstrate that NOTUM is highly expressed in human CRC and its expression positively correlates with the expression of FASN in tumor tissues." (PMID 39404424, 2024). "The overexpression of FASN indicates tumor progression in PTC, ATC, and FTC and PTC cell line TPC1, ONCO-DG-1, and B-CPAP, as well as ATC cell line 8505C and ATC primers culture cell line collected from the thyroid tissue patient." (PMID 39000236, 2024). "Metabolic druggable proteome upregulated in cold tumors such as FASN, whose inhibitor (cerulenin) is a potential candidate for inhibiting tumor growth and simultaneously boosting TME function." (PMID 38714665, 2024). "In order to further confirm the impact of SDHC on tumor invasion and metastasis through lipid accumulation, we utilized orlistat, a fatty acid synthase inhibitor, to decrease the presence of lipid droplets in SDHC knockdown cells." (PMID 38844980, 2024). "We have previously shown that inhibition of FASN using a novel TVB3664 inhibitor decreases tumor growth in the Pt2402 patient-derived xenograft model (PDX)." (PMID 38732103, 2024). "Pharmacological inhibition of FASN inhibited tumor growth and was an effective strategy for treating ccRCC." (PMID 38649345, 2024). "Overall, our results uncovers the CBR4/FASN/mTOR axis as a mechanism for tumor development and inspires us a new molecular guide for the therapeutic strategies for GEP‐NETs treatment." (PMID 39524139, 2024). "This raises the interesting possibility that aspects of the primary tumor such as hypoxia, cytokine, or immune exposure drive differential FASN expression and lipid metabolism in subsequent metastases." (PMID 39678343, 2024). "The ELISA results showed that TVB-3166 reduced the FASN gene of the tumor, consistent with the in vitro results." (PMID 38218866, 2024). "Tumor cells’ secretion of macrophage colony-stimulating factor (M-CSF) induces fatty acid synthase (FASN) in TAMs, which, in turn, promotes the production and secretion of immunosuppressive IL-10." (PMID 39119332, 2024).
tumor (continued). "Previous studies have mainly focused on the function of FASN in the proliferation and metastasis capability of tumor cells." (PMID 38272906, 2024). "Another FASN inhibitor, C75, decreased lymph node metastasis in cervical cancer and reduced the tumour burden in lung adenocarcinoma, albeit with a significant drop in mouse body weight." (PMID 38610991, 2024). "The TUNEL assay also corroborated that the overexpression of FASN inhibited apoptosis in tumor tissues." (PMID 39345091, 2024). "The protein levels of TC2N and FASN in cell lines and tumor specimens were monitored by qRT-PCR, WB, immunofluorescence and immunohistochemistry." (PMID 38167440, 2024). "The results demonstrated that the overexpression of FASN facilitated cell proliferation and inhibited the anti-tumor effect of ADM in SU-DHL-2 cells." (PMID 39345091, 2024). "Conversely, inhibiting FASN in lung cancer cells has been shown to promote tumor metastasis in vivo." (PMID 39624081, 2024). "Examination of FASN gene expression by bulk RNA-seq in TCGA cohort or another publicly available primary tumor dataset from the NCI demonstrated similar results at the RNA level with increases in FASN expression in tumors relative to unpaired benign samples." (PMID 38112617, 2024). "After FASN knockdown, the tumor growth rate was significantly repressed and the resistance of the tumor to gemcitabine was reversed." (PMID 38218866, 2024). "How can the metabolic tug-of-war between tumor and cytolytic immune cells be unbalanced by suppression of FASN alone?" (PMID 39349429, 2024). "Fatty acid synthase (FASN) is a key regulator of the lipid metabolic network, providing energy to favor tumor proliferation and development." (PMID 36650542, 2023). "We further identified that FASN expression was correlated with the tumor grade and metastasis of pNETs, and FASN was significantly up-regulated in pNET cells." (PMID 37283794, 2023). "For example, acetylation of FASN restrained lipogenesis required for tumour growth by controlling its stability." (PMID 37813994, 2023). "FASN inhibitors have been developed to improve the anti-tumor activity against various breast cancers." (PMID 37696831, 2023). "Modulated tumor microenvironment in response to FASN inhibition along with the reversal of multidrug resistance phenotype was linked with decreased expression of ABC proteins." (PMID 37256177, 2023). "Fatty acid synthase, a key enzyme for lipid metabolism, can promote tumor progression in several ways." (PMID 37784135, 2023). "Although inhibiting FASN alone or in combination with PI3K demonstrated a robust decrease in tumor growth, current FASN inhibitors have limited clinical applications because of certain pharmacological limitations." (PMID 36982568, 2023). "This indicates that TCM can inhibit tumor growth by interfering with FASN activity and affecting fatty acid production." (PMID 37497413, 2023). "Evidence has shown that inhibiting FASN in TAMs can significantly reduce extracellular tumor-promoting cytokines and hinder tumor progression." (PMID 37700339, 2023). "Next, the immunohistochemical results of subcutaneous xenografts also revealed that FASN expression level and tumor malignancy index KI67 decreased after OGDHL overexpression." (PMID 37626050, 2023). "They observed in mice orthotopically xenografted with GSCs that silencing FASN using shRNAs or inhibition with C75 decreased microvessels density and tumor growth." (PMID 36934087, 2023). "FASN, a pivotal rate-limiting enzyme in fatty acid synthesis, plays a major role in tumor growth and therapeutic resistance, suggesting a potential target in HCC-SR cells." (PMID 36604718, 2023). "Together, these observations strongly support a role for FASN in cell proliferation and tumor growth." (PMID 36934087, 2023).
tumor (continued). "In cancerous diseases, TRIM21 has been shown to facilitate tumor lipid metabolism via mediating ubiquitination and degradation of fatty acid synthase (FASN), one of the rate-limiting enzymes in the de novo lipogenesis pathway." (PMID 37249651, 2023). "According to in vitro data, in vivo dual blockade of HER2 and FASN also slowed tumor growth compared to the administration of T or TVB3166 as a monotherapy." (PMID 36753044, 2023). "Most tumor cells express higher levels of Acetyl-CoA carboxylase, fatty acid synthase (FASN), and lipogenic enzymes." (PMID 37021836, 2023). "Significantly, administration of orlistat in the high CSN6/FASN PDXs can hinder tumor growth as demonstrated by reducing tumor volume." (PMID 37202390, 2023). "An intervention known as C57, which targets FASN in TAMs, can reduce its secretion of pro-tumor inflammatory factors and exert a tumor-suppressive effect." (PMID 37700339, 2023). "Patient-derived xenograft experiments prove the effectiveness of employing orlistat and cetuximab combination in suppressing tumor growth for CSN6/FASN-high CRC." (PMID 37202390, 2023). "In parallel, fatty acid synthase (FASN) inhibitors are another important target of SFB for inducing apoptosis in tumor cells." (PMID 37175435, 2023). "As a result, tumor cells activate de novo fatty acid synthesis, and elevated levels of fatty acid synthase are negatively correlated with prognosis." (PMID 36768739, 2023). "We characterize the critical regulators of the FASN overexpression in tumor development, including EGF, CSN6, GSK3β, and E3 ligase FBXW7β." (PMID 37202390, 2023). "FASN is a key enzyme for FA de novo synthesis from glucose in tumor cells, and FAs are the basic material for the synthesis of phospholipids, which are the main component of the cell membrane in BC cells." (PMID 36765683, 2023). "Studies on TNBC also revealed fatty-acid synthase (FASN) as an attractive target for novel tumor-specific therapeutic strategies." (PMID 37628869, 2023). "Our results show a different role for FASN in the two tumor types, suggesting a different bioenergetic evolution." (PMID 36650542, 2023). "The expression of FASN also correlated with tumor stage and size indicating its prognostic value as a biomarker for tumor progression." (PMID 37046804, 2023). "Mechanistically, KDM5C exerted effects on tumor development by reducing H3K4me3 at specific promoters and downregulating its target gene fatty acid synthase (FASN)." (PMID 37185761, 2023). "Specifically, FASN inhibitors can induce ferroptosis in tumor cells by reducing the levels of intracellular TAG and PC and increasing the levels of PUFA in the membrane through the Lands cycle." (PMID 37064872, 2023). "The co-administration of the PI3K inhibitor (CYH33) with the FASN inhibitor (C75) has been found to synergistically inhibit tumor growth while enhancing host immunity." (PMID 37700339, 2023). "FASN expression was investigated in normal and tumor tissues by analyzing microarray data from two different databases, GLP96 and GLP570." (PMID 36650542, 2023). "Adipocytes increased the secretion of IGF-1 when co-cultured with BC cells, which increased the expression of fatty acid synthase (FASN) in tumor cells and promoted the growth and metastasis of BC." (PMID 36765683, 2023). "When co-cultured with MCF-7 BC cell lines, mouse 3T3-L1 adipocytes and human mammary adipocytes increased the release of IGF-1, which increased the expression of FASN in tumor cells and promoted the growth and metastasis of BC." (PMID 36765683, 2023). "Results showed that a high FASN level was link to a larger tumor size (OR, 2.04; 95% CI, 1.04-4.00; P = 0.038) and HER2 positivity (OR, 1.53; 95% CI, 1.05-2.23; P = 0.028)." (PMID 37124526, 2023). "Although increased levels of fatty acid synthase (FASN) in tumor cells lead to increased secretion of polyunsaturated FAs into the TME, TAMs increase their lipid levels through CD36 uptake of these polyunsaturated FAs." (PMID 37781517, 2023).
tumor (continued). "Further investigation into the mechanism of the lipid-lowering effects of ECD revealed that it downregulated ACSL4, ACSL1, CPT1A, and FASN levels in colorectal tissues and downregulated tumor formation in the colorectum." (PMID 37078067, 2023). "CAAs increase the expression of FASN in tumor cells to facilitate FA de novo synthesis from glucose." (PMID 36765683, 2023). "Significantly, administration of the FASN inhibitor orlistat or cetuximab alone impeded the tumor volume and tumor mass of CSN6-high PDXs with some efficacy, while a combination of these two drugs was more efficient in suppressing tumor growth." (PMID 37202390, 2023). "The combined inhibition of FASN and PI3Kα synergistically increased free fatty acids level in the tumor microenvironment." (PMID 36934087, 2023). "The tumor area exhibited elevated expression of FASN and increased de novo fatty acid biosynthesis coupled with decreased fatty acid oxidation." (PMID 37046804, 2023). "In patients with colorectal cancer, a significant reduction in gene expression and activity levels of lipoprotein lipase (LPL) and FASN was detected in adipose tissue adjacent to the tumor lesion compared to tissue distant from the neoplasm." (PMID 36670988, 2023). "Genetic knockdown of FASN in RB further confirmed its role in tumor cell proliferation and progression." (PMID 37046804, 2023). "The elevated level of FASN, observed in T-cell tumors, correlated with the decreased level of antitumor response by tumor-infiltrating macrophages." (PMID 37256177, 2023). "Subcutaneous tumours derived from CAND1 knockdown cells in a xenograft nude mouse model also exhibited downregulation of FASN, ACC1 and ACLY, enhanced oil red O staining and an increase in TAG content." (PMID 37837399, 2023). "The analysis and comparison of various tumor-related studies showed that the upregulated FASN gene expression and activity is negatively correlated with tumor immune infiltration." (PMID 37920207, 2023). "We found that FASN knockdown in tumor spheres inhibited their expressions of ALDH1 and OCT4, accompanied by impaired stem properties of such CSCs." (PMID 36809297, 2023). "Both silencing of FASN and treatment with FASN inhibitor inactivated the mTOR pathway, supporting a tumor suppressor role of FABP5 via inhibition of mTOR through FASN." (PMID 37416772, 2023). "A more detailed analysis based on tumor grade showed a significant reduction in FASN expression in advanced stage PDAC." (PMID 36650542, 2023). "Cerulenin is a fatty acid synthase inhibitor that induces apoptosis in various tumor cells and is an antifungal antibiotic that inhibits fatty acid and steroid biosynthesis." (PMID 37582698, 2023). "They revealed that the FASN inhibitor prevented the estrogen tumor-promoting effects of tamoxifen and completely restored the tamoxifen sensitivity in resistant BCCs overexpressing ER+/HER2 receptors." (PMID 38017510, 2023). "Next, using shRNA to knock down the FASN protein in Cr(VI)-transformed BEAS-2B cells, we saw a decrease in FASN protein expression and a loss of the xenograft tumor development of Cr(VI)-transformed BEAS-2B cells." (PMID 38069382, 2023). "Inhibiting FASN can reduce the energy source of tumor cells and inhibit the role of M2 macrophages and Treg cells, eventually hindering the growth of tumors." (PMID 38264667, 2023). "IHC was performed on microarrays from 71 HCC patients and adjacent tissues, and the IHC staining scores of FASN of tumor tissue specimens of HCC were significantly higher than those of paracancerous tissue specimens, which were analyzed by paired t-test." (PMID 36604718, 2023). "FASN is a key enzyme in FA anabolism, and FASN expression levels are markedly increased in many tumor cells." (PMID 36994237, 2023). "We observed that the total ACLY, pACLY, ACC1, and FASN expressions were increased in the Cr-tumor tissue as compared to the normal adjacent tissues." (PMID 38069382, 2023).